NBPF17P (NBPF member 17, pseudogene)
Synonyms: NBPF23; NBPF23P
Gene: Unprocessed pseudogene on chromosome 1 (143,595,216 to 143,635,641, reverse strand). Ensembl gene ENSG00000179571.
Diseases named in the same sentence as NBPF17P in open-access papers:
NBPF17P is named in the same sentence as 1 disease in open-access papers, as found by Europe PMC text mining. Sharing a sentence is not in itself a finding about the gene and the disease.
NBPF17P shares sentences with these, for which no sentence is quoted: neuroblastoma (1 paper).